GP5 (glycoprotein V platelet)
Description:
The GPIb-V-IX complex functions as the vWF receptor and mediates vWF-dependent platelet adhesion to blood vessels. The adhesion of platelets to injured vascular surfaces in the arterial circulation is a critical initiating event in hemostasis.
Synonyms: GPV; CD42d
Tractability: Antibody: its Gene Ontology location is reachable by antibodies, with high confidence; UniProt predicts a signal peptide or a membrane-spanning region. PROTAC: ubiquitination databases record sites on it.
Gene: Protein-coding gene on chromosome 3 (194,394,821 to 194,399,266, reverse strand). Ensembl gene ENSG00000178732.
Subcellular location: Membrane
Subcellular location (Human Protein Atlas): Cytosol
Pathways (Reactome):
Hemostasis: Amplification and propagation of coagulation cascade; FXIIa, PKa-dependent activation of coagulation pathway; GP1b-IX-V activation signalling; Platelet Adhesion to exposed collagen; Platelet Aggregation (Plug Formation); Regulation of clotting cascade
Disease: Defective F9 activation; Defective binding of VWF variant to GPIb:IX:V; Enhanced binding of GP1BA variant to VWF multimer:collagen
Gene Ontology:
Molecular function: protein binding
Biological process: blood coagulation, intrinsic pathway; positive regulation of platelet activation; release of sequestered calcium ion into cytosol; cell adhesion; megakaryocyte development
Cellular component: extracellular exosome; glycoprotein Ib-IX-V complex; plasma membrane; membrane
Genetic constraint (gnomAD): Loss-of-function variants: 0 observed, 0.47 expected, observed/expected ratio (o/e) 0, 90% interval 0 to 1.84. That is too few expected variants to judge how well the gene tolerates losing a copy. Missense variants: 739 observed, 714.47 expected, observed/expected ratio (o/e) 1.03, 90% interval 0.97 to 1.1. Synonymous variants: 371 observed, 344.52 expected, observed/expected ratio (o/e) 1.08, 90% interval 0.99 to 1.17.
Homologues: Orthologues: chimpanzee GP5 (99% identical), macaque GP5 (93% identical), pig GP5 (76% identical), mouse Gp5 (71% identical), rat Gp5 (71% identical), rabbit GP5 (67% identical), tropical clawed frog gp5 (33% identical). Paralogues in human: SLIT1 (24% identical), TLR9 (23% identical), LRRN2 (23% identical), SLIT3 (22% identical), SLIT2 (22% identical), SLITRK5 (22% identical), SLITRK6 (22% identical), SLITRK2 (21% identical), SLITRK4 (20% identical), SLITRK3 (20% identical), LINGO1 (20% identical), LRRN1 (20% identical), and 13 more.
Diseases named in the same sentence as GP5 in open-access papers:
GP5 is named in the same sentence as 75 diseases in open-access papers, as found by Europe PMC text mining. Sharing a sentence is not in itself a finding about the gene and the disease. The quoted sentences say what the papers report.
viral infection (19 papers, 2007 to 2025). "Endoplasmic reticulum (ER)-resident N-acetyltransferase 9 (Nat9) interacts with porcine reproductive and respiratory syndrome virus (PRRSV) glycoprotein 5 (GP5) and targets GP5 for K27-linked polyubiquitination and proteasomal degradation, suppressing viral infection." (PMID 40307900, 2025). "The N30, N34, N44 and N51 of four potential N-glycosylation sites of GP5 are related with viral infection and antigen characteristics." (PMID 28738888, 2017). "Viral infections have been detected by PCR using the MY09/MY11 oligoprimers alone or followed by nested PCR with GP5+/GP6+ primer pairs." (PMID 17201927, 2007). "In 2019, a DNA vaccine candidate containing PRRSV GP5-Mosaic sequences was shown to be immunogenic and induced protection of pigs against virus infection, supporting the potential for the mosaic vaccine to provide broader protection against emerging PRRSV variants." (PMID 35215994, 2022). "The GP5 protein could induce specific neutralizing antibodies and serotype-specific linear epitopes could neutralize viral infections in vitro." (PMID 24916952, 2014). "Moreover, upon viral infection, Co-IP experiments using nsp2-specific antibodies or N-specific antibodies revealed the formation of a complex between N and nsp2 with the M protein, GP2a, and GP5." (PMID 39601570, 2025). "Thus, it is reasonable for us to speculate here that GP2a/4 and GP5 mediate different and subsequent processes during the viral infection." (PMID 32727587, 2020). "However, the virus infection process may involve additional cell receptors, as other studies have suggested that the GP5/M complex binds sialoadhesin (CD169), another putative receptor involved in PRRSV entry." (PMID 31649651, 2019). "Notably, transgenic pigs lacking sialoadhesin are still susceptible to viral infection, implying that a GP5/M-sialoadhesin interaction is not necessary for PRRSV entry into permissive cells." (PMID 31649651, 2019). "Moreover, GP5 was a key protein for PRRSV invaded cells, and its glycosylation modification for viral infection was essential." (PMID 29546034, 2018). "However, whether and how the interactions between PRRSV GP5 and host proteins affect the viral infection process have not been well-studied." (PMID 37078873, 2023).
cervical carcinoma (14 papers, 2001 to 2025). A carcinoma arising from either the exocervical squamous epithelium or the endocervical glandular epithelium. "Our estimates of the risk of cervical cancer among high-risk HPV–positive women are based upon the systematic use of the GP5+/6+ test, which is validated for clinical purposes." (PMID 34652438, 2022). "The test was developed for identification of the 18 HR HPV genotypes associated with cervical cancer using GP5+/6+-PCR products." (PMID 23299934, 2013). "The test was developed for identification of the 18 HR-HPV genotypes associated with cervical cancer by using GP5+/6 + −PCR products." (PMID 24156822, 2013). "In a retrospective case–control study, we investigated high-risk HPV DNA presence by general primer GP5+/6+ PCR in the last normal cervical smear in the patient archives (i.e. baseline smear) of 57 women who later developed cervical cancer." (PMID 11487272, 2001). "Additionally, using PCR with GP6/GP5 HPV universal primers in 113 cervical cancer biopsies from Iranian women, a similar HPV-positive percentage rate was reported (78%)." (PMID 33238902, 2020). "HeLa cells (known HPV-positive cervical carcinoma) and SW579 (known HPV-negative thyroid carcinoma) were run in parallel as controls for both HPV consensus primer sets (MY09/MY11 and GP5+/GP6+)." (PMID 20175927, 2010). "Using the GP5+/6+ consensus primer they showed only a prevalence of 77% in cervical intraepithelial neoplasia (CIN), and 88% in cervical carcinoma." (PMID 12592370, 2003). "HPVs have been identified in 92.91% of a large series of cervical cancers collected internationally using PCR assays, of which 55 negative samples were tested again using HPV consensus GP5+/6+, E7 type-specific and CPI/II primers, where 72.7% were found to be positive for HPV." (PMID 25147721, 2014).
breast carcinoma (7 papers, 2011 to 2024). "This dichotomy of GP5 has been used previously and was significantly associated with probability of treatment discontinuation in a trial with breast cancer patients." (PMID 35031830, 2022). "We performed our study including 251 cases (breast cancer) and 186 controls (benign breast tumors), using three different molecular techniques with PCR (GP5/GP6, CLART® and DIRECT FLOW CHIP®)." (PMID 28482874, 2017). "EFC#93 is located within GP5, a gene coding for a surface glycoprotein which has been suggested to be involved in hematogenous breast cancer metastasis." (PMID 29268762, 2017). "There are identical sequence variations of a PCR product Gp5+ to Gp6+ in both the benign and later breast cancer." (PMID 26734565, 2015). "Based on this criteria 1 of the 10 (10%) normal tissue specimens was positive for HPV in the GP5+/6+ PCR and 13 of 80 (16%) breast cancer specimens were positive for HPV." (PMID 26658849, 2015). "We used both conventional and real time PCR assays with consensus (MY09/11, GP5+/GP6+) and type specific (HPV16 E6/E7) primers to detect HPV DNA sequences in tumors as well as corresponding blood samples of same breast cancer patients." (PMID 21247504, 2011).
prostate carcinoma (4 papers, 2022 to 2025). A carcinoma that arises from epithelial cells of the prostate gland. "From this origin, the prostate carcinoma of GP5 diverged into two major branches, A and B." (PMID 37828555, 2023).
dyslipidemia (3 papers, 2018 to 2024). "Based on these results, low levels of GP5 can increase the risk of IS, which is consistent with the association with Parkinson’s disease but contrary to the association with colorectal cancer, systemic lupus erythematosus, and dyslipidemia." (PMID 29699572, 2018).
gastric cancer (3 papers, 2019 to 2022). A primary or metastatic malignant neoplasm involving the stomach. "A novel peptide GP-5, isolated by whole-cell subtractive panning of the phage displayed 12-mer peptide library, has also been selected and binds specifically to gastric cancer (GC) cells and tissues." (PMID 30867462, 2019). "Recently, in vitro phage display using gastric cancer cells allowed the identification of DE532 (VETSQYFRGTLS) and GP-5 (IHKDKNAPSLVP) peptides, and specific antibodies to target gastric cancer." (PMID 33202648, 2020).
oral cancers (3 papers, 2010 to 2018). "A large multicentre study reported HPV DNA in 4% of 766 oral cancers using the consensus PCR primers GP5+/GP6+." (PMID 29580212, 2018). "Oral cancer specimens, however were previously typed using nested PCR MY09/MY11 followed by GP5+/6+ and sequencing of the PCR product." (PMID 20723234, 2010). "Also, the prevalence of HPV was numerically, but not significantly, lower in studies of oral cancers that analysed HPV DNA types either using other types of primers or those that did not report the primers used than those using GP5+/GP6+ primers." (PMID 25515630, 2014).
cervical intraepithelial neoplasia (2 papers, 2003 to 2022). "Noninferiority of the Onclarity HPV Assay on the COR instrument (Onclarity-COR) was assessed with the comparator assay glycoprotein 5–positive (GP5+)/6+ enzyme immunoassay (GP-EIA) for clinical sensitivity on 122 cervical intraepithelial neoplasia 2 and greater samples." (PMID 34546350, 2022).
nasal polyp (2 papers, 2015). "The frequently used method of HPV-detection was MY09/11 PCR Assay, applied to cryopreserved as well as paraffin-embedded nasal polyps, moreover GP5+/6+ PCR assay, HPV flow through hybridisation and gene chip method." (PMID 26509801, 2015). "In all 257 obtained tissue specimens (166 nasal polyps, 39 antrochoanal polyps and 52 nasal turbinates) gDNA was extracted and studied by broad spectrum PCR assays GP5+/6+, SPF and NMPCR, relative to tissue fixation method." (PMID 26509801, 2015).
Sepsis (2 papers, 2020 to 2025). Sepsis is defined as life-threatening organ dysfunction caused by a dysregulated host response to infection. "The profile of MYL9 associated gene interactions for adult sepsis is quite different than that for pediatric sepsis, with association instead with platelet membrane glycoproteins GP5 and GP6, PLOD2, COL6A3, and PROS1." (PMID 32318053, 2020). "It was found that, after further adjustment for age, sex, FBG, UA, ALT, AST, and CVD, two glycans (GP5 and GP14) were negatively associated with sepsis, and two glycans (GP21 and GP22) were positively associated with sepsis." (PMID 40165956, 2025). "In addition, the combination of serum GP4 with other study measures (such as GP5 and GP9) in patients with sepsis significantly improved the prediction of the risk of death in the hospital." (PMID 40165956, 2025). "Firstly, we used the LASSO and RFE algorithms to filter 24 initial N-glycans and optimize the complexity of the model, identifying 6 initial N-glycans (GP1, GP5, GP14, GP20, GP21 and GP24) for sepsis." (PMID 40165956, 2025).
anal carcinoma (1 paper, 2010). "Genomic DNA from the anal cancer samples was used for GP5+/6+ primer PCR, a conserved region within HPV, both positive controls for HPV cancer cell lines (Hela, CaSki, SiHa) and negative controls were used to validate results." (PMID 20939896, 2010).
autism (1 paper, 2025). Persistent deficits in social interaction and communication and interaction as well as a markedly restricted repertoire of activity and interest as well as repetitive patterns of behavior. "We used wide-field calcium imaging to measure neural responses in the olfactory bulb of mouse models of autism using the C57BL/6J-Tg(Thy1-GCaMP6f) GP5.11Dkim/J." (PMID 41062277, 2025).
cervical (1 paper, 2006). "The prevalence of cervical HPV was 66.1% (238 of 360): 114 samples were positive with the MY09/MY11 primer pair, 50 were positive with the GP5+/GP6+ primer pair, and 74 were positive by nested PCR." (PMID 16832413, 2006).
cervical tumors (1 paper, 2018). "Using the published GP5/GP6 PCR protocol we established our HPV positive cancer sample sets of 137 oropharyngeal and 121 cervical tumors." (PMID 30161236, 2018).
co-infection (1 paper, 2017). "Although we successfully generated PRRSV VLPs using the recombinant baculoviruses expressing Gp5, M, N and E proteins, we noticed the VLPs formation in the recombinant baculovirus co-infection model we used was not very efficient." (PMID 28403874, 2017).
dysplasia (1 paper, 2013). A usually neoplastic transformation of the cell, associated with altered architectural tissue patterns. "PCR MY/PGMY 09/11 and Amplicor showed 2.75 (95% CI: 1.16–6.53, P = 0.02) and 3.01 (95% CI: 1.05–8.63, P = 0.04) times higher accuracy in detecting dysplasia lesions than PCR GP5+/6+." (PMID 23930214, 2013).
genital wart (1 paper, 2009). "We compared PGMY09/11, MY09/11 and GP5+/6+ primers sets in PCRs of 34 clinically diagnosed samples of genital warts, cervical brushings (with associated histological diagnosis) and vulval biopsies." (PMID 20003490, 2009). "PGMY09/11 primers detected HPV presence in more cervical brushing (100%) and genital wart (92.9%) samples compared to MY09/11 (90% and 64.3%) and GP5+/6+ (80% and 64.3%) primer sets, respectively." (PMID 20003490, 2009).
gram-positive bacterial infections (1 paper, 2025). Infections caused by bacteria that retain the crystal violet stain (positive) when treated by the gram-staining method. "Combination therapy (GP5, GP9) effectively normalized these parameters, closely approximating those of the uninfected control group (GP1), and highlighting its therapeutic potential in managing both Gram-negative and Gram-positive bacterial infections." (PMID 40672366, 2025).
hepatic cirrhosis (1 paper, 2021). "The apparent disappearance of the hepatic cirrhosis revealed in all STZ/MET/DEN, STZ/DEN/MET, and STZ/MET/DEN/MET treated groups (Gp3, Gp4, and Gp5, respectively)." (PMID 33440701, 2021).
hypertriglyceridemia (1 paper, 2022). A laboratory test result indicating elevated triglyceride concentration in the blood. "The GP5-mediated adhesion of platelets to injured vascular surfaces in the arterial circulation is a critical initiating event in hemostasis and apolipoproteins (APOs) may increase the risk of postprandial hypertriglyceridemia associated with cardiovascular disease." (PMID 36145440, 2022).
hypopharyngeal carcinoma (1 paper, 2018). Carcinoma, predominantly squamous cell, arising from the epithelial cells of the hypopharynx. "HPV DNA was assessed by GP5+/6+-PCR and by in situ hybridization in the 67 p16-positive cases, which resulted in a total of 30 HPV-positive cases (28 oropharyngeal, 1 laryngeal, and 1 hypopharyngeal carcinoma) in our series (all were HPV type 16)." (PMID 30513772, 2018).
influenza (1 paper, 2025). An acute viral infection of the respiratory tract, occurring in isolated cases, in epidemics, or in pandemics; it is caused by serologically different strains of viruses (influenzaviruses) designated A, B, and C, has a 3-day incubation period, and usually lasts for 3 to 10 days. "GP5 correlated negatively with RIG-I in COVID19 and influenza." (PMID 40825056, 2025).
invasive ductal carcinomas (1 paper, 2005). "In the present study, application of the GP5+/GP6+ assay using an arbitrary DNA quantity in the PCR indicated 5/26 (19%) invasive ductal carcinomas were HPV positive." (PMID 16288661, 2005).
leukemia (1 paper, 2025). A malignant (clonal) hematologic disorder, involving hematopoietic stem cells and characterized by the presence of primitive or atypical myeloid or lymphoid cells in the bone marrow and the blood. "Finally, public RNA-seq data from 93 leukemia cell lines for the identified NKX6-3 target genes show reduced activity of CD109 and overexpression of GP5 and MPP7 in RCH-ACV and MHH-CALL-3, highlighting the suitability of these cell lines as models for their investigation in follow-up studies." (PMID 41153416, 2025).
melanoma (1 paper, 2022). A malignant, usually aggressive tumor composed of atypical, neoplastic melanocytes. "Standardised delta scale Cochran–Mantel–Haenszel statistics calculated across cancer sites showed large DIF (≥ 1.5) between some sites (e.g. HCC, melanoma, CLL); however, there was no overall and consistent pattern of large DIF for GP5 across cancer sites." (PMID 35031830, 2022).
metastatic tumor (1 paper, 2023). "Consistent with this, a “wall” of nonmetastatic tumor existed at mid-prostate, where the tumor originated in GP5, while GP5’s metastatic tumor evolved as it migrated to and spread from the prostate apex." (PMID 37828555, 2023).
oropharyngeal carcinoma (1 paper, 2015). Carcinoma, predominantly squamous cell, arising from the epithelial cells of the oropharynx. "For example, in oropharyngeal carcinomas the long approved general PCR Assay GP5+/6+ has been proven more sensitive than MY09/11 PCR Assay, especially in low viral load samples." (PMID 26509801, 2015).
pharyngeal cancer (1 paper, 2014). "Additionally, HPV prevalence was numerically, but not significantly, lower in pharyngeal cancer studies that assessed HPV DNA types using other type primers than in those that used either GP5+/GP6+ or MY09/MY11 primers." (PMID 25515630, 2014).
prostatic intraepithelial neoplasia (1 paper, 2025). "Classes corresponding to higher-grade Gleason patterns (other GP4 subtypes, GP5) and prostatic intraepithelial neoplasia (PIN) were largely underrepresented or absent in the training set, and consequently, their classification accuracies were close to a random classifier." (PMID 40791488, 2025).
tonsillar cancer (1 paper, 2014). "The prevalence of HPV was numerically, but not significantly, lower in studies of tongue and tonsillar cancer that had analysed HPV DNA types using only a primer that included GP5+/GP6+ than in studies using alternative primers." (PMID 25515630, 2014).
type 1 diabetes (1 paper, 2022). "IgG high-mannose glycans (GP5) were significantly increased in children with type 1 diabetes relative to their healthy siblings (OR = 1.53, p=3.89 × 10−3)." (PMID 35622127, 2022).
type 2 diabetes (1 paper, 2020). "In this study, we found that GP3, GP5, and GP20 were increased in the type 2 diabetes individuals while GP22 and GP24 were decreased." (PMID 32587867, 2020). "We found and replicated that GP3, GP5, GP20, GP22, GP24, and several IgG-derived traits could compose a glycan score to discriminate the type 2 diabetes individuals from the health controls effectively for the first time." (PMID 32587867, 2020).